NRG1 (neuregulin 1)
Diseases named in the same sentence as NRG1 in open-access papers (continued):
Sharing a sentence is not in itself a finding about the gene and the disease.
schizophrenia (continued). "The roles of AKT1 and NRG1, either alone or their interaction, through which they might contribute to a susceptibility to social function in schizophrenia are worth further investigation." (PMID 25688191, 2014). "Indeed, a novel missense mutation (Val to Leu) in the TMc domain of NRG1 was reported to be associated with schizophrenia, suggesting a potential causal mutations within this gene." (PMID 24782733, 2014). "Both stress and Nrg1 may have converging effects upon N-methyl-D-aspartate receptors (NMDARs) which are implicated in the pathogenesis of schizophrenia, sensorimotor gating and dendritic spine plasticity." (PMID 25324742, 2014). "Moreover, a meta-analysis found NRG1 as one of the most consistent genes to be reported in schizophrenia, underlining the role of NRG1 as schizophrenia susceptibility gene." (PMID 24683514, 2014). "NRG1 risk genotypes or haplotypes have been associated with schizophrenia." (PMID 24478629, 2014). "Neuregulin-1 (NRG1) is one of the best-validated schizophrenia susceptibility genes." (PMID 24683514, 2014). "Both ErbB4, as well as Nrg-1 have been identified as risk genes for schizophrenia." (PMID 24592210, 2014). "Finally, NRG1 5′ and 3′ SNPs rs4560751 and rs3802160 polymorphisms (likelihood ratio test p = 0.00020) interacted with schizophrenia, and contributed to inefficient cortical activation during a working memory task in HC." (PMID 24976857, 2014). "It will be interesting to assess whether schizophrenia-associated mutations result in impairments in Nrg1-induced activation of p110δ-associated PI3K signaling and protein synthesis, suggesting parallels with p110β dysregulation in FXS." (PMID 24592210, 2014). "In addition, a report recently indicated that a common missense variant in the NRG1 gene is associated with both schizophrenia and sudden cardiac death." (PMID 24887423, 2014). "Interestingly, kalirin-7, NRG1, and ErbB4 are highly and specifically expressed in GABAergic interneurons, and have been associated with schizophrenia." (PMID 25309333, 2014). "Since both BDNF and NRG1 are implicated in the pathophysiology of schizophrenia, we examined whether the interaction between TrkB and ErbB4 is altered in schizophrenia." (PMID 25052836, 2014). "We could not detect any significant influence of variation in the studied Neuregulin 1 and Neuregulin 3 polymorphisms on cognitive performance or on gamma noise power magnitudes in patients with schizophrenia." (PMID 24976857, 2014). "Genetic variation in NRG1 was associated to an increased risk for developing schizophrenia." (PMID 24976857, 2014). "There is another fundamental question whether schizophrenia is associated with the upregulation or downregulation of the NRG1-ErbB4 signaling." (PMID 24949465, 2014). "Karl as well as Chohan and co-workers focus on the role the schizophrenia susceptibility gene neuregulin 1 (NRG1) might play in the context of GxE interactions." (PMID 25566003, 2014). "Collectively, our results indicate that double deficiency of Akt1 and Nrg1 can result in the impairment of social cognitive functions, which might be pertinent to the pathogenesis of schizophrenia-related social cognition." (PMID 25688191, 2014). "Candidate gene studies have identified a number of genes, such as catechol-O-methyltransferase (COMT), brain-derived neurotrophic factor (BDNF), neuregulin-1 (NRG-1), and disrupted in schizophrenia (DISC-1) that appear to be shared risk factors for schizophrenia, bipolar disorder, and MDD." (PMID 25202283, 2014). "This review will summarize preclinical data to assess if Nrg1 might be mediating an increased risk to environmental factors with relevance to schizophrenia (i.e., stress and cannabis) and experimental animal research (i.e., laboratory housing conditions)." (PMID 23966917, 2013).
schizophrenia (continued). "A gene trap of this type located within NRG1 (Neuregulin 1) is an intriguing finding as there is considerable (albeit not yet concrete) genetic evidence associating variants in this gene with increased risk of schizophrenia and bipolar disorder 44–47." (PMID 23577691, 2013). "Our results suggested that the binding of CDXA/E2F/HFH2 and S8/NKX2/CDXA to the NRG1 block increased the schizophrenia risk in European populations, and their dissociation and association of TATA and CDP CR transcription factors might be protective." (PMID 23301017, 2013). "Since neuregulin 1 is one of the susceptibility genes for schizophrenia, MMN may be an intermediate phenotype that links genes to schizophrenia." (PMID 24069006, 2013). "Moreover, increased grey and white matter volumes in association with a schizophrenia risk allele-carrier status have also been described for a Neuregulin-1 at-risk SNP in childhood-onset schizophrenia." (PMID 22580710, 2013). "Our analysis highlights the importance of this particular NRG1 block in schizophrenia, such that the combination of different alleles of these SNPs within the corresponding block might have an impact on the regulation of NRG1 gene expression." (PMID 23301017, 2013). "The authors concluded that the experience of psychosocial stress during adolescence may trigger further pathophysiological features that contribute to the development of schizophrenia in individuals underlying NRG1 gene abnormalities." (PMID 23966917, 2013). "Importantly, a NRG1 polymorphism interacts with psychosocial stress thereby affecting reactivity to expressed emotions in schizophrenia patients and NRG1 also interacts with job strain thereby increasing the risk of heart disease." (PMID 23966917, 2013). "Adolescent Nrg1 HET mice displayed a trend toward increased expression of the pro-apoptotic and inflammatory cytokine TNF-α in the hippocampus and schizophrenia patients with a missense mutation in the transmembrane domain of NRG1 show heightened expression of TNF-α from B cells." (PMID 23447498, 2013). "Moreover, Neuregulin 1, a susceptibility gene of schizophrenia, has been shown to increase the release of GABA." (PMID 23922840, 2013). "In summary, these animal studies provided the very first evidence for an interaction between the schizophrenia risk gene Nrg1 and cannabis and implied that stress and gender may also influence these interactions." (PMID 23447438, 2013). "Also, similar social dysfunctions to the ones observed in Npas4-KO mice have already been observed in mice characterized by alterations in the inhibitory pathways such as the TgNL2.6 strain or in neuregulin 1, the schizophrenia risk gene, knockout mice." (PMID 23029555, 2012). "Genetic data from a new population is valuablebecause it addresses whether NRG1 play a crucialrole in predisposition to schizophrenia in a distinctpopulation." (PMID 23508206, 2011). "NRG1 is one among several candidate genes linked to a relevant behavioural disease, schizophrenia." (PMID 21991932, 2011). "Indeed, two schizophrenia susceptibility genes encoding the trophic factor neuregulin 1 (NRG1) and its receptor ErbB4 (ERB4) have been shown to facilitate activity-dependent GABA release from PV-positive basket cells in the mouse prefrontal cortex." (PMID 21876820, 2011). "Therefore, its position as well as function,strongly supports the NRG1 gene as a susceptibilitygene for neuropathological disorderssuch as bipolar disorder and schizophrenia." (PMID 23508206, 2011). "Since COMT, AKT1, and ErbB-signaling are each implicated in both cancer and schizophrenia, NRG1-ErbB signaling in B lymphoblasts provides a biologically plausible research tool for elucidating cellular mechanisms relevant to both cancer biology and neurobiology." (PMID 20520724, 2010). "Evidence of association between the NRG1 (Neuregulin-1) gene and schizophrenia has been documented." (PMID 21637446, 2009).
schizophrenia (continued). "Finally, our adhesion studies and findings have brought at least three promising schizophrenia susceptibility genes–NRG1, COMT, and Akt1–together in a coherent, biologically plausible framework." (PMID 18159252, 2007). "Numerous studies have investigated the association between schizophrenia and NRG1." (PMID 17598910, 2007). "Our findings suggest that a mechanism of the NRG1 genetic association with schizophrenia may involve the molecular biology of cell adhesion." (PMID 18159252, 2007). "Genomewide linkage analysis on large Icelandic pedigrees showed evidence for linkage with an initial LOD score of 3 on chromosome 8p13, which led to the identification of the Neuregulin-1 gene (NRG1) as a potential genetic risk factor (O.R. = 2) for schizophrenia." (PMID 17598910, 2007). "Additionally, NRG1 has been identified in GWAS and MRI studies, with the SNP rs12467877 showing a significant association with lateral ventricle enlargement, a hallmark feature of schizophrenia." (PMID 40943654, 2025). "Future works are warranted to study the role of NRG1-ErbB4 signaling in the formation and function of synapse between mitral and granule cell, and whether disruption of NRG1-ErbB4 signaling in the OB causes olfactory dysfunction that is commonly observed in schizophrenia patients." (PMID 37147705, 2023). "Here we investigated if genetic risk for schizophrenia could affect drug reward and reinforcement for cocaine in an established mouse model of genetic risk for schizophrenia, the neuregulin 1 transmembrane domain heterozygous (Nrg1 TM HET) mouse." (PMID 37233814, 2023). "In addition to being previously associated with BD, depression, and schizophrenia, the expression levels of the NRG1 gene in different brain regions were associated with matter abnormalities, clinical symptoms, and cognition in a recent study conducted in a transdiagnostic psychiatric cohort." (PMID 36422266, 2022). "Hence, we made an assumption that the significant upregulation of NRG1 in FGR mice mPFC may be one main cause of schizophrenia behavior induced by FGR." (PMID 36460658, 2022). "In addition, susceptible genes, such as NRG1 (Neuregulin 1), and its receptor ErbB4, have received considerable attention as a plausible pathological mechanism of schizophrenia due to their crucial role in neurodevelopment and modulation of glutamatergic and GABAergic signaling." (PMID 35272593, 2022). "However, the mutation of genes NRG1 or ErbB4 may only account for a small part of schizophrenia cases." (PMID 33897409, 2021). "In addition, proteins structurally and functionally closely linked to NMDAR, like NRG1 display strong positive genetic association with schizophrenia, whereas abnormal cortical oscillations triggered by NMDAR dysfunction represent an electrophysiological endophenotype of schizophrenia." (PMID 34899420, 2021). "Notably, IL17a identified alterations in signaling by ERBB2 factors, which is a pathway of particular relevance to schizophrenia given its interaction with neuregulin-1 to mediate cell adhesion, its potential role in schizophrenia risk, as well as antipsychotic response/treatment." (PMID 34158620, 2021). "Thus, the oligodendroglial association between this pathway and schizophrenia may be another potential alteration linking NRG1 to the development of the disorder." (PMID 32425837, 2020). "This study provided the first direct evidence for the association between schizophrenia risk variant and creativity in healthy subjects, and suggested that NRG1 rs6994992 might be among the many risk variants that underlie the genetic link between schizophrenia and creativity." (PMID 31649580, 2019). "Therefore, it is tempting to speculate that the observation of schizophrenia-related phenotypes after anti-NRG1 dosing is caused by antibody-mediated inhibition of full length NRG1 shedding." (PMID 29844389, 2018).
schizophrenia (continued). "Thus, we assessed whether molecular alterations exist in the endocannabinoid signalling pathway during brain development in a mouse model for the schizophrenia risk gene neuregulin 1 (Nrg1)." (PMID 29467679, 2018). "Presynaptic neuregulin 1 (Nrg1) to postsynaptic ErbB signaling contributes to excitatory synapse formation and plasticity, and disturbances in this signaling are thought to contribute to a number of structural and functional endophenotypes associated with schizophrenia." (PMID 28275713, 2017). "It will provide new insights into how BACE1-dependent NRG1 proteolytic processing could contribute to the pathophysiology of schizophrenia, and help to discover the underlying biomarker of schizophrenia, which is essential for early diagnosis of the disorder disease and effective medical treatment." (PMID 28993723, 2017). "The majority of these genes play critical roles in brain development, such as the NRG1-ErbB4 signaling pathway that is involved in glia cell differentiation, myelination, neuronal migration, axon guidance, synapse formation, and synaptic plasticity; all deficient in schizophrenia." (PMID 26733804, 2015). "Previous studies had indicated that NRG1 is a signalling protein that mediates cell-cell interactions and it is essential for the development and function of multiple organ systems and its dysregulation has been linked to diseases such as breast cancer, schizophrenia and HSCR." (PMID 22574178, 2012). "Moreover, because almost 80% of SNPs studied belonged to only two associations with very large genes (NRG1 - Schizophrenia/PARK2 - Parkinson's disease) a third analysis removing these two genes was performed and the same correlation between FST and φ was detected (ρ = 0.152, p < 10-5, n = 821)." (PMID 21261943, 2011). "As NRG1 has been found to predict higher risk of schizophrenia and bipolar disorder, and is linked with axonal myelination and migration, these authors hypothesize a mechanistic link between NRG1 within the anterior thalamic radiation and risk for psychotic disorders." (PMID 20339554, 2010). "The Neuregulin 1 gene was first reported in studies of schizophrenia within the Icelandic population, which also has a risk haplotype that was found to confer the greatest risk in bipolar disorder with mood-incongruent psychotic features and schizophrenia with mania." (PMID 20300526, 2010). "However, studies published in 2009, suggest that multiple SNPs of the NRG1 gene might cause schizophrenia in certain groups of people, but that population stratification also plays a role in the onset of schizophrenia." (PMID 19445674, 2009). "Recently, molecular alterations in ERBB4/HER4 receptor (loss-of-function) or in NRG1 have been linked to several neurological diseases such as amyotrophic lateral sclerosis (ALS) and schizophrenia." (PMID 38369520, 2024). "Further studies are required to develop drugs that specifically target nNOS in NRG1-ErbB4 signaling pathways to treat schizophrenia." (PMID 38396027, 2024). "Given correlations between genetic variations within the NRG1 locus and schizophrenia, Klein employed the DMF method to simulate neural activities and study the association between the NRG1 gene expression levels and neural E–I balance." (PMID 38979037, 2024). "The interaction between NRG1 and ErbB4 is believed to play a role in the pathological mechanisms of schizophrenia." (PMID 38433839, 2024). "Another study investigating cognitive functions in patients suffering from schizophrenia and the impact of NRG1 rs35753505 on cognition found similar correlations between genotype status and semantic verbal fluency." (PMID 39518545, 2024). "Despite the fact that NRG1 rs35753505 is the most reported single marker for schizophrenia, a clear role of its genotype related to cognitive function in this disorder has not been established yet." (PMID 39518545, 2024).
schizophrenia (continued). "In contrast, the low level of NRDC observed in our study infers an interesting relationship between NRG1 and schizophrenia." (PMID 38694089, 2024). "In conclusion, our study demonstrates that NRG1 is involved in the formation of interhemispheric callosal connections and provides a novel perspective on the relevance of NRG1 in excitatory neurons and in the etiology of schizophrenia." (PMID 38918041, 2024). "Nrg1 (Neuregulin 1) type III, a susceptible gene of schizophrenia, exhibits a critical role in the central nervous system and is essential at each stage of Schwann’s cell development." (PMID 38136627, 2023). "We prepared rodent models of schizophrenia by subcutaneously injecting EGF or neuregulin-1 into neonatal rats and mice." (PMID 36830741, 2023). "In contrast to EGF model rats, schizophrenia model mice established by postnatal treatment with neuregulin-1 display a variety of behavioral abnormalities depending on the neuregulin-1 splicing variants administered." (PMID 36830741, 2023). "The analysis resulted that the gene set extracted by the systematic review is strongly associated with genes differentially expressed in schizophrenia (p ≤ 0.0001422) with reference to DISC1 and NRG1." (PMID 36831241, 2023). "A post-mortem study showed that in the PFC of schizophrenia patients, there was an increase in NRG1-induced ErbB4 activation and increased ErbB4/PSD-95 interaction, responsible for the suppression of NMDAR signaling activation." (PMID 36983018, 2023). "The connection of the EGF family with the pathogenesis of schizophrenia is particularly well documented in the case of neuregulin-1, structurally very similar to EGF." (PMID 38004423, 2023). "Other susceptibility genes of schizophrenia such as desmocollin 1 (DSC1) and neuregulin 1 (NRG1) had also been identified to play a vital role in regulating neuronal progenitor proliferation." (PMID 36313621, 2022). "Studies demonstrate that NRG1 is significantly upregulated in prefrontal cortex and hippocampus of schizophrenia patients." (PMID 36460658, 2022). "Neuregulin 1 (NRG1) and its receptor ErbB4 are susceptibility genes of schizophrenia, and endogenous NRG1-ErbB4 signaling is critical to maintaining GABAergic activity, especially in PVIs." (PMID 36359279, 2022). "Recently, the NRG1/ErbB4 signaling pathway emerged as a candidate therapeutic target for schizophrenia." (PMID 35876932, 2022). "Mutant NRG1 mice display both excitatory and inhibitory synaptic impairment and schizophrenia-like behavioral disorder." (PMID 35606871, 2022). "Recent studies have found increased NRG1 signaling in the PFC of schizophrenia patients, which stimulates GABA transmission." (PMID 36460658, 2022). "Improving the GABAergic maturation of PV interneurons through NRG1 knockdown in mPFC significantly rescued the schizophrenia behaviors in FGR mice." (PMID 36460658, 2022). "Genes and proteins that have been linked to the regulation of spine morphology and development, such as Neuregulin-1 and ErbB4 or Cdc42, show aberrant expression or signaling in schizophrenia patients." (PMID 35496908, 2022). "In this study, we proved that NRG1 was pivotal in FGR induced schizophrenia and NRG1 knockdown in mPFC rescued schizophrenia symptoms in FGR mice." (PMID 36460658, 2022). "Previous studies have pointed out the role of NRG1 and its receptor ErbB4 in the pathophysiology of schizophrenia." (PMID 35876932, 2022). "Experimental studies showed that both downregulating and upregulating NRG1–ErbB4 signaling-induced schizophrenia-like abnormal behavior." (PMID 35876932, 2022). "Collectively, our study provides direct evidence that NRG1 is a critical molecule that bridges PV interneuron GABAergic maturation and schizophrenia behaviors in offspring with FGR." (PMID 36460658, 2022).